SOX2 (SRY-box transcription factor 2)
Diseases named in the same sentence as SOX2 in open-access papers (continued):
Sharing a sentence is not in itself a finding about the gene and the disease.
melanoma (continued). "SOX2 is known to be instrumental in tumorigenesis in multiple cancer types; however, its role in melanoma has been controversial." (PMID 31080551, 2019). "Moreover, SOX2 has been associated with stemness and tumor initiating cells (TICs), proposed to explain origin and heterogeneity of many tumors, including cervical, lung, ovarian, head and neck squamous cell carcinoma, medulloblastoma, skin squamous-cell carcinoma, and melanoma." (PMID 30466459, 2018). "In conclusion, with this study we would propose a thigh correlation between SOX2 expression and OxPhos metabolism in melanoma cells, under a condition of reduced HIF1α expression." (PMID 30466459, 2018). "We found that 2-DG promotes cell death in SOX2-silenced cells grown in standard pH conditions and, most importantly, also in acidic melanoma cells depleted of SOX2." (PMID 30466459, 2018). "Flow cytometry and western blot analyses showed increased SOX2 expression in A375-M6 melanoma cells exposed to acidic medium (pH 6.7) compared to control (pH 7.4)." (PMID 30466459, 2018). "While an early paper reported that SOX2 silencing reduces in vivo growth of A2058 melanoma cells, recent studies suggest that SOX2 is dispensable for melanomagenesis and metastasis formation." (PMID 30466459, 2018). "Here we show for the first time that SOX2 is highly expressed in melanoma cells exposed to extracellular acidosis, where it modulates cell metabolism in order to favor an oxidative phenotype, possibly interfering with HIF1α expression." (PMID 30466459, 2018). "To further confirm the metabolic effects of SOX2 downregulation, we tested the efficacy of two metabolic drugs in control and SOX2-silenced A375-M6 melanoma cells maintained in standard condition (pH 7.4) or exposed to extracellular acidosis (pH 6.7)." (PMID 30466459, 2018). "In A375-M6 melanoma cells, extracellular acidosis increases SOX2 expression, that sustains the oxidative cancer metabolism exploited under acidic conditions." (PMID 30466459, 2018). "Here we correlate for the first time SOX2 expression in acidic melanoma cells with a more oxidative metabolism, that is in turn associated with tumor progression and poor prognosis." (PMID 30466459, 2018). "CAGE also binds to the sex-determining region y-box 2 (SOX2) and induces cancer stem cell-like properties in melanoma cells." (PMID 30583572, 2018). "Recent studies have pointed out the crucial role of the transcription factor SOX2 (sex-determining region Y (SRY)-Box2) in melanoma and cancer in general." (PMID 30466459, 2018). "Consistently, overexpression of SOX2 in 501-Mel melanoma cells drastically reduced HIF1α mRNA and protein expression." (PMID 30466459, 2018). "In SOX2-silenced control and acidic melanoma cells, we observed reduction of PDP2 and an appreciable increase of PDK1, suggesting an impaired mitochondrial OxPhos." (PMID 30466459, 2018). "This is likely true mainly in conditions when SOX2 exceeds HIF1α in terms of protein expression, as in the case of acidosis-exposed melanoma cells." (PMID 30466459, 2018). "Only SOX2, the expression of which was shown to require the Hedgehog signalling in melanoma and is crucial for the self‐renewal and tumorigenicity of human melanoma‐initiating cells 34, sharply increased in three cell lines with induced low MITF." (PMID 29369499, 2018). "This change in metabolism elicited by SOX2 silencing was also evident in melanoma cells exposed to extracellular acidosis (pH 6.7), confirming the contribution of SOX2 to the OxPhos metabolic adaptation." (PMID 30466459, 2018). "This conclusion was reached through experiments of SOX2-enforced expression and knockdown in melanoma cells." (PMID 29156643, 2017). "While SOX2 expression has been identified in cancer models, there is only limited information of SOX2 in melanoma." (PMID 28636992, 2017). "In the field of oncology research, SOX2 functions as an oncogene in many types of tumors, including malignant melanoma." (PMID 28129648, 2017).
melanoma (continued). "The deletion of Sox2 in melanoma or SCC caused regression of tumors, and a number of genes involved in proliferation, stemness, and cell survival are regulated by Sox2 in these tumors, providing further evidence of a role for Sox2 in carcinogenesis." (PMID 28191771, 2017). "We next investigated if SOX2 upregulation can rescue melanoma cells from ASA-induced inhibition of cell survival and induction of apoptosis." (PMID 28636992, 2017). "Our study shows that the expression level of miR-625 is inversely correlated with the expression profile of SOX2, and SOX2 reversed the inhibitory effect of miR-625 in malignant melanoma." (PMID 28129648, 2017). "In summary, the present studies describe a novel mechanism by which ASA suppresses the in-vitro and in-vivo growth of highly aggressive B16F10 melanoma tumors via SOX2-dependent-PAF-R independent signaling pathway." (PMID 28636992, 2017). "Since SOX2 overexpression increases the self renewal ability of melanoma cells thus generating stem-like cells, we used this model as well as sorted ALDHhigh/low cells to study the effect of phenformin on the stem cell compartment in melanoma." (PMID 28036292, 2017). "In previous studies, the expression of SOX2 was upregulated in melanoma tissues and cells, and SOX2 invasion, self-renewal, and tumorigenicity of melanoma cells." (PMID 28129648, 2017). "Our next studies determined if PGF2α and FGF-1 that modulate SOX2 expression, can rescue melanoma cells from AL8810-induced inhibition of survival, and compared the responses with ASA." (PMID 28636992, 2017). "The present studies describe a novel mechanism by which ASA suppresses the in-vitro and in-vivo growth B16F10 melanoma tumors via SOX2-dependent-PAF-R-independent pathway." (PMID 28636992, 2017). "We then wanted to confirm these results by assessing the effect of phenformin in a cellular model of melanoma that overexpresses the widely known stem cell marker SOX2." (PMID 28036292, 2017). "The results showed that ectopic expression of SOX2 reversed the inhibitory effect of miR-625 on cell proliferation and migration in malignant melanoma." (PMID 28129648, 2017). "In the present study, we demonstrated successful reprogramming of terminally differentiated melanoma TILs that express high levels of PD-1 into human iPSCs by using SeV vectors encoding OCT3/4, SOX2, KLF4, and c-MYC." (PMID 27057178, 2016). "Recently, H3K9 demethylation and Sox2 gene expression have been reported to be essential for the elevation of self-renewal capability of differentiated melanoma cells." (PMID 26683522, 2016). "SOX2is regulated by HH signaling where transcriptionfactorsGLI1 and GLI2 directly bind to the proximal promoter region of SOX2 in primary melanoma cells.Also, human SOX14 expression is GLI1 dependent in U87MG cells and SHH dependent in U87MG and HepG2 cells." (PMID 26588701, 2015). "Our focus turned to ID4, as SOX2 had been previously shown to be expressed in human melanoma tissues." (PMID 25642713, 2015). "Specifically, Sox2 was detected in individual cases of melanoma, lung small cell and adenocarcinoma, clear cell renal cell carcinoma, squamous cell carcinoma, and poorly-differentiated carcinomas of unproven origin." (PMID 25713758, 2015). "The melanoma CSC markers SOX2, KLF4, and CD271 exhibited reduced expression profiles in the A375 IGFBP5 OE cells compared to empty vector control cells." (PMID 26010068, 2015). "Analysis of mRNA expression levels of CD271, CD133, ABCB5, SOX2 and melanoma markers SOX10, NES and TYR, MART-1 and MITF-M revealed a strong heterogeneity among the PM tissue samples." (PMID 24799129, 2014). "Santini and colleagues investigated SOX2 in melanoma initiating cells and Hedgehog-GLI (HH-GLI) signaling." (PMID 25114775, 2014). "For example in melanoma, SOX2 knockdown in A2058 cells resulted in a 4.5-fold decrease in invasion in vitro and adopted this phenotype via the upregulation of matrix metalloproteinase (MMP)-3." (PMID 25114775, 2014).
melanoma (continued). "U343, U373 and the melanoma line 93.04A12.1 expressed 0.6102, 0.4258 and 0.0001 transcripts SOX2 per transcript β-actin, respectively." (PMID 17375044, 2007). "We summarize the structure, glycosylation and regulation of CD24, then discuss its role in melanoma, supporting phenotypic plasticity, sustaining stem-like populations and promoting resistance to BRAF-targeted and cytotoxic therapies through SOX2/STAT3-linked programmes." (PMID 42126185, 2026). "In melanoma, STAT3 activation causes SRY box 2 (SOX2) to be upregulated." (PMID 39944829, 2025). "In addition, overexpression of Notch1 in CAFs inhibits the stemness of tumor cells, while inhibition of Notch1 in CAFs leads to increased expression of stemness markers (Sox2, Oct4, Nanog) in melanoma CSCs." (PMID 40806546, 2025). "The expression of SOX2 in oral canine melanomas may function as a suppressor or activator in alternative signaling pathways, as observed in in vitro studies." (PMID 41012776, 2025). "Recent reports demonstrate that SOX2 expression may be present in 50% of melanomas related to neoplastic invasion." (PMID 41012776, 2025). "Moreover, in primary melanoma cells, the activation of this signaling cascade promotes the expression of Sox2, the transcription factor well known for its crucial role in self-renewal and tumorigenicity of melanoma CSCs." (PMID 39199632, 2024). "Dual gene silencing of FMOD and SOX2 ablated VM and subsequent melanoma brain metastases." (PMID 38635031, 2024). "Thus it was shown in melanoma cell lines that p38-dependent phosphorylation and thereby activation increases SOX2 stability and transcriptional activity." (PMID 38475835, 2024). "SOX2 is a target of miR-145-5p since it is downregulated by this miRNA, and its expression promotes the proliferative, migratory, and invasive abilities of melanoma cells." (PMID 39684214, 2024). "CDK1 orchestrates a dual mechanism by directly engaging with the pivotal cancer stemness-related protein Sox2 to drive tumor initiation in melanoma, while simultaneously preserving tumor stemness characteristics and pluripotency through phosphorylating TFCP2L1 in human bladder cancer." (PMID 37743465, 2023). "In addition to Sox2, microphthalmia-associated transcription factor (MITF) is a marker of melanoma cell differentiation." (PMID 37614365, 2023). "In addition, we identified Mesenchyme (COL1A1+), Endothelium (SOX18+, KDR+), proliferating cells (TOP2A+, MKI67+), and some off‐target cells; Glial (MSX1+, SOX2+), Melanoma (PMEL+, PLP1+), and Neuron (DLL3, HES6)." (PMID 35322595, 2022). "Notably, silencing of SOX2 in these cells was sufficient not only to prevent this increase but also to almost completely abrogate self-renewal ability of A375 and A2058 melanoma spheres." (PMID 35944584, 2022). "We then investigated whether the endogenous level of SOX2 alters the response of melanoma cells to BRAF-targeted therapy." (PMID 35944584, 2022). "Interestingly, melanospheres derived from dex-stimulated parental (adherent) melanoma cells displayed a remarkable increase in stem cell markers (Oct3/4, AP-1, E2f1, Sox2 and NANOG), and that this increase was TDO-mediated." (PMID 35847038, 2022). "The invasiveness of malignant melanoma is attributed by some authors to SOX2 overexpression." (PMID 35719931, 2022). "Interestingly, dose-response curves of several BRAFV600E melanoma cells showed that higher SOX2 protein levels correlate with lower sensitivity to PLX4032." (PMID 35944584, 2022). "We first evaluated whether SOX2 could desensitize melanoma cells to BRAF inhibition by knocking down SOX2 in A375, A2058, and SK-MEL-5 cells." (PMID 35944584, 2022). "SOX2 is one of the Yamanaka cell factors and is a poor prognostic factor in melanoma." (PMID 35624662, 2022). "Additionally, SOX2 has already been shown to induce CD24 expression in a melanoma cell or a murine model." (PMID 34293822, 2022).
melanoma (continued). "However, only genetic and pharmacological inhibition of p38 is able to revert the increase of SOX2 protein induced by PLX4032, suggesting p38 as a major compensatory mechanism responsible for BRAFi-induced increase of SOX2 in melanoma cells." (PMID 35944584, 2022). "To address whether BRAF inhibition induces SOX2 expression in melanoma, we treated A375, SK-MEL-5, and A2058 cells, which express BRAFV600E, with PLX4032 (vemurafenib) and GSK2118436 (dabrafenib), two selective BRAFi." (PMID 35944584, 2022). "Similarly, we found a significant positive association between HIF1α and SOX2 (R = 0.49, p-value = 0.0089) along with CD44 and SOX2 (R = 0.39, p-value = 0.045) in melanoma cancers." (PMID 35186918, 2022). "However, our results suggest that SOX2 plays an important role in early stage adaptive response, likely representing an emergency plan to allow melanoma cells to survive from death induced by BRAFi." (PMID 35944584, 2022). "We hypothesize that MDR induced by BRAFi in melanoma cells could be promoted by SOX2 through a direct transcriptional regulation of ABCG2." (PMID 35944584, 2022). "In addition, leveraging Usp9x-dependent SOX2 ubiquitination has been reported to overcome the adaptive resistance induced by BRAFi in melanoma." (PMID 35944584, 2022). "Further, Sox2 is known to regulate self-renewal and tumorigenicity of melanoma cells." (PMID 35847038, 2022). "We also evaluated the in vitro capability of plasma concentrations of PSPC1 and TGFβ protein to induce CSC-TF expression in melanoma cells, finding that SOX2 might be regulated by both proteins under IH conditions." (PMID 34359789, 2021). "Indeed, extracellular acidosis was demonstrated to increase SOX2 expression in melanoma, confirming that SOX2 is also able to influence cancer cell metabolism profile to a more oxidative phenotype through the hypoxia-inducible factor 1-α (HIF1α) pathway." (PMID 34768751, 2021). "We further demonstrated that SOX2 and Usp9x proteins were moderately upregulated in metastatic melanoma patients, and we hypothesized that SOX2 stabilization by Usp9x drives protein expression necessary for melanoma growth, survival and invasion." (PMID 33613844, 2021). "Moreover, SOX2 expression in melanoma patient samples was found to correlate with increased tumor thickness." (PMID 33613844, 2021). "We further demonstrated that Usp9x KD led to SOX2 proteasomal degradation in melanoma." (PMID 33613844, 2021). "Thus, inducing degradation of SOX2 via Usp9x inhibition is a promising therapeutic approach to overcome this adaptive resistance in melanoma." (PMID 33613844, 2021). "First, we noted that vemurafenib induced SOX2 protein in melanoma cells." (PMID 33613844, 2021). "We found that SOX2 KD blocked colony growth in melanoma (3D culture)." (PMID 33613844, 2021). "In fact, in the case of melanoma, it has been thought that tumor initiation may be prevented by the deletion of the SOX2 gene and that the removal of SOX2-positive cells from established tumors may lead to regression." (PMID 33613850, 2021). "Hence, our data suggest that Usp9x depletion leads to robust kinase inhibitor induced apoptosis of melanoma cells which is most likely mediated by decreased SOX2 protein." (PMID 33613844, 2021). "Based on ourresults, enhancement of SOX2 at the mRNA and protein level in tumor tissuesas well as melanospheres, can enhance the expression of miR-9, which results in an increasedmotility of melanoma cells through reduction of CDH1 level." (PMID 34308569, 2021). "Patient-derived SSM2c melanoma cells were transfected with the reporter along with SOX2 or GLI1." (PMID 33958721, 2021). "We hypothesized that if Usp9x and SOX2 play an essential role in melanoma cell growth, SOX2 and Usp9x should be co-overexpressed in melanoma." (PMID 33613844, 2021). "Overexpression of SOX2 controls self-renewal and tumorigenicity of melanoma." (PMID 33613844, 2021).
melanoma (continued). "Previous studies have shown that SOX2 KD suppresses cell growth and induces apoptosis in melanoma." (PMID 33613844, 2021). "To date, the role of SOX2 has been controversial in melanoma." (PMID 34768751, 2021). "Moreover, SOX2 was an independent prognostic factor for poor survival and resistant to anti-PD-1 therapy in melanoma with PD-L1 high expression." (PMID 33158915, 2020). "SOX2 overexpression is observed in different types of malignancies, including squamous cell lung carcinomas, squamous cell esophageal carcinomas, oral squamous cell carcinomas, melanoma, sinonasal carcinomas, Ewing’s sarcoma and ameloblastic carcinoma." (PMID 31967981, 2020). "As expected, SAHA sensitized the melanoma cells to T-cell killing and partially reversed SOX2-induced CD8+ T-cell tolerance, indicating that the function of SAHA might be achieved through targeting SOX2." (PMID 33158915, 2020). "Interestingly, melanoma TIC population has been demonstrated to depend on SOX2 expression, that we found up-regulated under acidic conditions." (PMID 32803272, 2020). "In addition, SOX2 regulates survival, self-renewal, and tumorigenicity of human melanoma-initiating cells and participates in dormancy regulation of melanoma tumor-repopulating cells." (PMID 33203881, 2020). "SOX2 regulated the self-renewal of human melanoma-initiating cells." (PMID 32033067, 2020). "SOX2 OE promoted melanoma growth as confirmed by the growth curve of the xenografts volume." (PMID 33158915, 2020). "TGF-β induced SOX2 expression and promoted the invasion and metastasis of melanoma cells." (PMID 32439916, 2020). "Given that SAHA decreased SOX2 expression and recovered the sensitivity of melanoma cells to T-cell killing, we hypothesized that SAHA could enhance the effect of anti-PD-1 in vivo." (PMID 33158915, 2020). "SOX2 KD enhanced the sensitivity of melanoma cells to T-cell killing." (PMID 33158915, 2020). "In SKMEL28 melanoma cells, only Sox2 and Bmi1 showed a 2-fold upregulation when treated with bFGF." (PMID 30675361, 2019). "Notably, SOX2 has been validated as a target of miR-625, as it induced migration and invasion in melanoma and esophageal cancer." (PMID 30988674, 2019). "Taken together, bFGF could induce Sox2 in melanoma cells which remained largely unaffected in NBMEL and the nevomelanocytes with the exception being C139N." (PMID 30675361, 2019). "These HIF1α variations might be enough for the metabolic changes observed in our experimental models of SOX2-manipulated melanoma cells." (PMID 30466459, 2018). "We observed a MCT1 reduction and MCT4 increase in SOX2-depleted melanoma cells." (PMID 30466459, 2018). "Indeed, SOX2 has been reported to regulate self-renewal and tumorigenicity of human melanoma-initiating cells." (PMID 30466459, 2018). "Given the results obtained after modulation of SOX2 expression in melanoma cell lines grown in acidic and standard conditions, we hypothesized the involvement of HIF1α transcription factor in SOX2-driven metabolic adaptation." (PMID 30466459, 2018). "Indeed, SOX2 silencing in melanoma cells, under both standard and acidic conditions, favored an enhanced expression of glucose transporters GLUT-1 and GLUT-3." (PMID 30466459, 2018). "Nestin and SOX2 are embryologic stem cell transcription factors that bind an enhancer region on the nestin gene, and they are preferentially co-expressed in metastatic melanomas when compared with nevi or primary melanomas." (PMID 29455657, 2018). "Our results indicate that HIF1α and SOX2 are inversely correlated in normoxic condition, and this effect might be functionally sufficient to reprogram melanoma cells toward OxPhos." (PMID 30466459, 2018). "Thus, for a high expression of SC marker SOX2, which is critical for forming the tumour‐initiating cells in melanoma 34, low‐MITF level is required." (PMID 29369499, 2018). "Consistently, phenformin reduces melanoma cell viability and growth independently from SOX2 levels." (PMID 28036292, 2017).